DRD2 (dopamine receptor D2)
Diseases named in the same sentence as DRD2 in open-access papers (continued):
Sharing a sentence is not in itself a finding about the gene and the disease.
depression (continued). "Depression-like behaviors were observed more pronounced in DRD2 knockout (DRD2−/−) mice than wild-type mice following chronic stress." (PMID 35308874, 2022). "l-SPD, which has a unique pharmacological profile of DRD1 agonism and DRD2 antagonism exerted antidepressant-like effects on the CMS model of depression." (PMID 36059987, 2022). "The relationship of NAc neurons in rats that co-express DRD1 and DRD2, forming D1-D2 heterodimers, with depression is unclear." (PMID 36059987, 2022). "This study focused on the changes of DRD2 expression in the VTA in stress-induced depression and found that maternal deprivation reduced the expression of DRD2 gene." (PMID 35308874, 2022). "This study aims to investigate the effect of DNA methylation of DRD2 gene on early life stress–induced depression in adult rats." (PMID 35308874, 2022). "The DRD2 agonist Ropinirole (ROPI) can be used as an antidepressant drug for the treatment of depressive disorders." (PMID 35053133, 2022). "Another study examined the effect of violent victimization and the relationship between depression-like symptoms and the dopamine D2 receptor gene (DRD2), while analyzing potential race- and sex-specific variations." (PMID 34573220, 2021). "In contrast, photostimulation of Drd2 expressing pyramidal cells was ineffective across anxiety-like and depression-like measures." (PMID 30644390, 2019). "Significant associations between DRD2, DRD4, and COMT polymorphisms and the risk of depression, as well as the severity of depressive symptoms, were reported." (PMID 26733829, 2015). "Based on such findings, dopaminergic targets have become a focus for depression therapies; one study found that the DRD2 agonist pramipexole was as effective as fluoxetine in the treatment of MDD." (PMID 24834916, 2014). "Amygdalar genes that were changed across treatment groups also were related to psychological conditions such as depression (Drd2), stress enhanced fear learning (Gabra4), chronic mild stress (Drd1a), and anxiety, mood disorders, and psychoses (Htr3a)." (PMID 25165739, 2014). "Likelihood of increased smoking level rose 2-fold with each additional DRD2/ANKK1 rs1800497 minor allele, with a pronounced association among adolescents with depression symptoms." (PMID 24927283, 2014). "The DRD2/ANKK1 Taq1A polymorphism (rs1800497) affects striatal D2 receptor binding, with the A1 allele associated with reduced binding in healthy individuals but increased binding in depression." (PMID 41373485, 2025). "In Study‐2 (longitudinal survey), we found that the norm adaptation capability and long‐term mental health (i.e., self‐reported depression) shared both phenotypic correlation and common genetic influences, and DRD2 influenced mental health via the mediating role of norm adaptation capability." (PMID 39679781, 2025). "DRD2 is the target of anti-psychotic medications and consistently appears as a significant locus across GWAS for psychiatric disorders and symptoms, including major depression, depressive symptoms, anhedonia, suicide, and addiction." (PMID 40400235, 2025). "Methylation analyses of 9 promoter/regulatory regions of genes known to be implicated in depression/PTSD (ADCYAP1, BDNF, CRHR1, DRD2, IGF2, LSD1/KDM1A, NR3C1, OXTR, SLC6A4) were performed on DNA from blood samples by the MassARRAY EpiTYPER platform, with MassCleave settings." (PMID 36001138, 2023). "Depression-like behaviors induced byovariectomy were associated with decreased RASD2 and DRD2 protein levels in thehippocampus, and Rasd2 overexpression in the hippocampus alleviateddepression-like behaviors and increased DRD2 expression." (PMID 36566472, 2023). "When DRD2 is activated, the level of cAMP in cells decreases, and the expression of DRD2 increases significantly, which not only inhibits the production of cAMP but also affects the production of DA, thus leading to depression and anxiety." (PMID 36624423, 2023).
depression (continued). "DRD2 together with β-catenin may serve as a potential predictive biomarker for worse prognosis as well as therapeutic target of GBM patients with depression." (PMID 37415171, 2023). "Collectively, long-term changes in the methylation of DRD2 promoter and its expression in the VTA induced by maternal deprivation may be related to the increased risk of developing depression later in life." (PMID 35308874, 2022). "In addition, mice with depression also had significantly lower DRD2 expression compared with control mice." (PMID 35053133, 2022). "In addition to playing an important role in the pathogenesis of psychological diseases, such as anxiety and depression, the DRD2 gene also plays a certain role in the pathogenesis of chronic diseases, such as sleep disorders." (PMID 34594253, 2021). "In addition, DRD2 had an indirect effect on depression severity mediated through the triangular part of the inferior frontal gyrus (indirect effect = -.01, SE = .00, 95% CI = [-.02, -.00])." (PMID 33690643, 2021). "The researchers showed that violent victimization was associated with higher levels of depression symptoms in African American females when they carried at least one A1 allele of the DRD2 gene, an effect not observed in Caucasian women or men of either race." (PMID 34573220, 2021). "The strongest one was observed between DRD2 and the frequency of alcohol consumption (p = 2.88E−08), followed by associations between the same gene (DRD2) and SCZ (p = 1.55E−07), CYP2D6 and SCZ (p = 1.81E−06), CHRM2 and major depressive disorder (p = 2.56E−06)." (PMID 31628418, 2021). "In addition, social isolation of Flinders Sensitive Line rats, genetic model of depression, reduced Drd2 expression in several areas in the striatum." (PMID 29141007, 2017). "Moreover, a recent study suggests the importance of the Par-4/DRD2 signaling pathway in major depression and bipolar disorder." (PMID 23029138, 2012). "Recently, DRD2 was identified as a gene contributing to PCOS development (polymorphisms in DRD2 may predispose individuals to the development of PCOS), and concomitantly, DRD2 was reported to increase the risk for type 2 diabetes and depression, both of which can coexist with PCOS." (PMID 39425884, 2024). "However, it should be further clarified that early life stress may enhance vulnerability to depression through changing DNA methylation of DRD2 gene in adulthood." (PMID 35308874, 2022). "Similarly, DRD2 is involved with anxiety, depression, and social dysfunction." (PMID 34950028, 2021). "This study predicted that linalool, p-cymene, α-terpinene, terpinen-4-ol, and α-terpineol primarily contribute to CBEO’s anti-depressant effect, mainly via interactions with OPRM1, PTGS2, ESR1, SLC6A4, DRD2, and NR3C1, the six depression-related targets." (PMID 38567354, 2024). "We identified pleiotropic loci 11q23.2 (mapped gene: NCAM1/DRD2) and 18q12.2 (mapped gene: CELF4) in neuroticism and IBS/GERD, supporting the genetic overlap between neuroticism and depression." (PMID 40226707, 2024). "More importantly, glioma patients with concomitantly high DRD2 and β-catenin have shorter overall survival than patients with concomitantly low expression, suggesting that the combined detection of DRD2 and β-catenin could be a key outcome measure in glioma patients with depression." (PMID 37415171, 2023). "Remarkably, the levels of DRD2 and β-catenin in tumor tissues from GBM patients with depression were significantly upregulated and negatively correlated with the prognosis of patients." (PMID 37415171, 2023). "Five important depression targets identified using the network map (GRIN2B, GRIN2A, DRD2, SLC6A4, and MAOA) and twenty-one related active compounds were selected for molecular docking." (PMID 33746756, 2021).
depression (continued). "This study aims to estimate the contribution of 11 polymorphisms in the genes SLC6A4 (5HTT), HTR1A, HTR2A, HTR1B, SLC6A3 (DAT1), DRD4, DRD2, COMT, and BDNF to suicidal behavior and severity of symptoms of depression and anxiety in the Russian population." (PMID 34199792, 2021). "One limitation is that several other dopamine receptors (such as DRD2 and DRD3), as well as other GABAA receptor subunits (such as α2, α3, β1, and δ), are also obviously involved in the regulation of depression." (PMID 33863350, 2021). "In this study, we estimated the contribution of SLC6A4 (5HTT), HTR1A, HTR2A, HTR1B, SLC6A3 (DAT1), DRD4, DRD2, COMT, and BDNF genes to the suicidal behavior and severity of symptoms of depression and anxiety in the East-Slavic population of Russia." (PMID 34199792, 2021). "First, we validated the finding that MS results in anxiety and depression-like behavior, which, in conjunction with lesional expression of ADRB2 and DRD2, provides evidence that HPA/SMA axes are involved." (PMID 32532293, 2020). "Our previous study demonstrated that DRD2 expression was significantly downregulated in the striatum of MD and CUS rats, which significantly correlated with depression-like behaviors." (PMID 23922862, 2013). "Five drugs met these criteria: Topiramate in ATC N03AX (treating epilepsy, targeting GABRA4), Desipramine, Imipramine, and Nortriptyline in ATC N06AA (treating depression and anxiety, targeting BDNF) and Methylphenidate in ATC N06BA (treating ADHD, targeting DRD2)." (PMID 39070649, 2024). "In a comprehensive meta-analysis of depression, recent GWAS involving millions of participants have identified common comorbidities with SUD, highlighting crucial correlations with the expression of NEGR1 in the hypothalamus and DRD2 in the NAc." (PMID 39635461, 2024). "DRD1 and DRD2 are expressed on glutamatergic PYR neurons in the PFC, but the role of D1 and D2 receptors expressed in PFC PYR in depression and antidepressant responses is largely unknown." (PMID 36059987, 2022). "Among GWAS genes that interacted the most with depression portrait genes were the histone acetyltransferase, EP300, the Rho GTPase, RHOA, the heat shock protein HSPA1A, the dopamine receptor, DRD2, the glutamate receptor, GRM5, the huntington gene, HTT, and the estrogen receptor, ESR2." (PMID 33589676, 2021). "related genes of dopamine system (DRD2, COMT), HPA axis system (CRHR1), and immune system (IL-1β SNP), can also interact with the environment to affect the occurrence of depression in a gender-specific manner." (PMID 33193645, 2020). "The unique and selective DRD2-selective partial agonist (−)-IHCH7041 may provide the medical community with chemical tools for exploring signaling pathways that counteract the efficacy and side effects of psychiatric disorders such as depression." (PMID 36059987, 2022). "In contrast, DRD2 mRNA and DRD2 protein expression negatively correlated with immobility time, suggesting that DRD2 may play a more important role than DRD1 in the development of stress-induced depression." (PMID 23922862, 2013). "Moreover, a recent postmortem study showed that Par-4 protein levels were decreased by 31% and 67% in the temporal cortices of bipolar disorder and major depression patients, respectively, without significant decreases in the DRD2 levels." (PMID 23029138, 2012). "Individual genes that commonly emerge among these studies include those with existing links to depression, such as DRD2 and FADS1, as well as novel genes such as NEGR1 and RPL31P12 without existing links to depression." (PMID 37076454, 2023). "miR-504 may mediate the downregulation of DRD1 and DRD2 expression in the nucleus accumbens, but DRD2 not DRD1 is involved in stress-induced depression in the animal models tested in this study." (PMID 23922862, 2013).
Parkinson disease (134 papers, 2009 to 2026). A progressive degenerative disorder of the central nervous system characterized by loss of dopamine producing neurons in the substantia nigra and the presence of Lewy bodies in the substantia nigra and locus coeruleus. "Therefore, we investigated the neuroprotective role of Netrin‐1 in dopaminergic neurons, focusing on its regulation of DRD2/GSK3β signaling and its potential to suppress ROS generation key pathways implicated in Parkinson's disease progression." (PMID 41249856, 2025). "Loss of function in striosomal Drd2-type SPNs could in turn downregulate dopamine release and lead to parkinsonism." (PMID 40943492, 2025). "DRD2 (a member of D2-like family), which is encoded by the DRD2 gene, is a receptor for the neurotransmitter dopamine and a target for antipsychotic drugs as well as Parkinson’s disease treatment." (PMID 37566075, 2023). "Of the five DARs and their variants, the DRD2 and its properties continue to be the most actively investigated because it is the main clinical target for antipsychotics and for the dopamine agonist treatment of Parkinson's disease." (PMID 25522365, 2014). "For example, the phenotype conferred by the human rs6277 allele of DRD2 has been successfully modeled in zebrafish using morpholinos against drd2a, and zebrafish models of neurodegeneration are being employed to identify mechanisms and treatments for Parkinson’s disease." (PMID 36040978, 2022). "Dopaminergic neurotransmission plays a crucial role in motor function through the coordination of dopamine receptor (DRD) subtypes, such as DRD1 and DRD2, thus the functional imbalance of these receptors can lead to Parkinson's disease." (PMID 39562043, 2025). "DRD2/DRD3 agonists are currently used in clinical neurology as symptomatic treatment for neurological conditions such as Parkinson’s disease and restless leg syndrome." (PMID 40358175, 2025). "Systemic DRD2 agonists, which are generally given for Parkinson’s disease, provide protection against exudative age-related macular degeneration via blocking choroidal neovascularization." (PMID 39012703, 2024). "Bromocriptine and cabergoline are known drugs targeting DRD2 and are clinically used to treat pituitary adenomas and Parkinson’s disease." (PMID 35463319, 2022). "Specifically, according to the theory of do-pamine receptor blockade, the symptoms of parkinsonism emerge when more than 80% of striatal dopamine 2 receptors (DRD2) are blocked." (PMID 36551993, 2022). "Intriguingly, DRD2 is the primary target for both typical and atypical antipsychotic drugs and for drugs used to treat Parkinson’s disease." (PMID 35491423, 2022). "For the potential therapeutic role of DRD2, more researches are needed like applying Bromocriptine, a proved DRD2 agonist used for Parkinson's disease." (PMID 33859743, 2021). "In the 10th injection, down-regulated genes were significantly enriched in terms of “Parkinson’s disease” and “Dopaminergic synapse” (such as Th, Drd2, Slc6a3, and Slc18a2)." (PMID 32997292, 2021). "Among the agents able to prevent aggregation of the mutant ataxin-1 and the consequent neurotoxicity, bromocriptine methylate (BRC), a potent DRD2 agonist approved for the treatment of Parkinson’s disease, showed promising results in ALS preclinical studies." (PMID 28236105, 2017). "Drd2−/− mice have abnormal gait similar to that of individuals with Parkinson disease, and the administration of antipsychotic medications (e.g., risperidone, a dopamine D2 receptor antagonist) has proven efficacious in treating symptoms associated with ASDs." (PMID 22559203, 2012). "Although DRD2 agonists generally benefit nutrient metabolism, the use of these drugs is sometimes associated with the development of impulse control disorders, including binge and compulsive eating, in patients with Parkinson's disease, which may lead to excessive weight gain and insulin resistance." (PMID 21603181, 2011).
Parkinson disease (continued). "In addition, we observed simultaneous α‐synuclein hyperphosphorylation and DRD2 downregulation, both of which are key pathological features in Parkinson's disease." (PMID 41249856, 2025). "As regards rigidity, there is only one report on 126 African-Caribbean patients showing a positive association with −141 C Ins/Del SNPs in DRD2, even though it was referred to antipsychotic-induced parkinsonism and not idiopathic PD." (PMID 33917417, 2021). "Drd2 is also the primary target of both antipsychotics and Parkinson’s disease medications." (PMID 30604007, 2019). "Concurrently, matrix Drd2-SPN and Drd1-SPN dysfunction may disrupt indirect and direct pathways, and together with dopamine fluctuations, these circuit-level changes could underlie the emergence of parkinsonism and chorea." (PMID 40943492, 2025). "Also consistent with this general hypothesis, it has been shown that stimulation of the low-affinity receptor DRD2 in astrocytes attenuates neuroinflammation in a mouse model of Parkinson’s disease." (PMID 36428964, 2022). "Therefore, the clinical intervention of DRD2 agonists and beta-blockers is of great value and attraction, especially because these drugs are known to be used in the treatment of other indications such as Parkinson’s disease." (PMID 34194334, 2021). "Moreover, Drd2 is the primary target of antipsychotics and Parkinson’s disease medications." (PMID 30604007, 2019). "Noteworthy, TH, dopamine receptor 2 (DRD2), SLC6A3/DAT, SLC18A2, tubulin beta 2A (TUBB2A), tubulin alpha 4A (TUBA4A), and tubulin beta 3 (TUBB3) were the 7 key genes enriched in the Parkinson disease pathway." (PMID 40259945, 2025). "Quinpirole and ropinirole are dopamine receptor D2 (DRD2) agonists and are bothused experimentally and for the clinical management of Parkinson's diseasesymptoms." (PMID 33183165, 2021). "Dimerization of PKM2 can promote the dopamine D2 receptor (DRD2) in astrocytes to promote dopamine biosynthesis through GSH synthesis regulated by PKM2-mediated Nrf2 transactivation, thus providing a potential target for Parkinson’s disease." (PMID 35967360, 2022). "Interestingly, the association of m434 with neuromuscular processes controlling balance was supported by dopamine receptor D2 (DRD2) and parkin (PARK2), both of which are regarded as key molecules for parkinsonism." (PMID 31582723, 2019). "The finding of downregulation of Drd2 in striatum in this study is highly relevant since mutant animals lacking Drd2 are akinetic and bradykinetic, with significantly reduced spontaneous movement that resembles the extrapyramidal symptoms of Parkinson's disease." (PMID 27375740, 2016).